INSL3 (insulin like 3)
Diseases named in the same sentence as INSL3 in open-access papers (continued):
Sharing a sentence is not in itself a finding about the gene and the disease.
cryptorchidism (continued). "A better picture of the role of INSL3 in cryptorchidism would involve harvesting small biopsies from the undescended testes, which might raise ethical issues due to the difficulties of obtaining informed consent." (PMID 37189986, 2023). "Based on the data provided in the 12 studies, INSL3/GREAT mutations are not as important in the development of cryptorchidism in humans as previously thought." (PMID 37733393, 2022). "In our study, LH, testosterone, and INSL3 levels were similar between cryptorchid and control groups, suggesting that Leydig cell function and/or number was preserved among boys with a history of cryptorchidism during puberty." (PMID 36073163, 2022). "We previously found that boys with cryptorchidism persisting at 3 months had decreased INSL3 levels in cord blood and elevated serum LH to INSL3 ratio at 3 months of age, which suggested decreased Leydig cell function in cryptorchid boys during the perinatal period." (PMID 36073163, 2022). "In Danish case-control studies on cryptorchidism, amniotic fluid DEHP and DiNP metabolite and PFOS levels associated positively with amniotic fluid testosterone (T) levels and negatively with amniotic fluid Insulin-like peptide 3 (INSL3) levels." (PMID 34690925, 2021). "Insl3 knockout in mice leads to cryptorchidism, indicating that it is important for testis descent." (PMID 32849262, 2020). "Context: Insulin-like peptide 3 (INSL3), a protein hormone produced by Leydig cells, may play a crucial role in testicular descent as male INSL3 knockout mice have bilateral cryptorchidism." (PMID 31611843, 2019). "When INSL3 values for weeks 13–16 are corrected for gestational age by converting to MoM, we still observe a significant difference in the mean values for controls versus both cryptorchids and hypospadias cases." (PMID 29740335, 2018). "In their prospective study including 3 groups (control, Danish and Finnish cryptorchidic boys), they could first clearly establish the physiological ontology of testicular INSL3 secretion in boys." (PMID 30687232, 2018). "This is strongly echoed by studies on the effects of maternal exposure to phthalates in rats where the fetal Leydig cells are seen as primary targets for this endocrine disruptor, leading to a reduction in both INSL3 and testosterone production as well as cryptorchidism." (PMID 30083133, 2018). "Using a case–control design, we show that cryptorchidism and hypospadias are both significantly associated with increased amniotic concentration of INSL3 during gestational weeks 13–16, and some, though not all steroid biomarkers." (PMID 29740335, 2018). "Epidemiological links of hypospadias and cryptorchidism withreduced fertility, and theobservations of reduced insulin-like factor 3 (INSL3) and increased gonadotropin levels in cryptorchid boys compared with healthy boys supports an associated testiculardysfunction in these disorders." (PMID 24316680, 2014). "An alternative mechanism for the reported increased incidence of cryptorchidism could be via effects on Insl3, a key factor in testicular descent in rodents." (PMID 23620786, 2013). "Although decreased blood INSL3 levels and mutations in Insl3/RXFP2 genes have been linked to a small number of human cryptorchidism cases, functions of the INSL3-RXFP2 system in species other than mice are largely unknown." (PMID 21138583, 2010). "Poor cell surface expression and failure to bind INSL3 or respond to the ligand with cAMP signaling was observed in the functional analysis of the variant protein, concluding that recessive endowment of variants of the RXFP2 gene can lead to genetic familial cryptorchidism." (PMID 37189986, 2023). "INSL3 acts as a significant biomarker for Leydig cell differentiation in the fetus and may be reduced by maternal exposure to endocrine disrupting chemicals, such as xenoestrogens or phthalates, leading to cryptorchidism." (PMID 35464060, 2022).
cryptorchidism (continued). "The fact that ibuprofen exposure affects testosterone and Insl3 production only during specific periods of human fetal testis development, has implications for the potential of this analgesic to impact testis descent, i.e. cryptorchidism (which is under the control of these two hormones)." (PMID 30869130, 2019). "Knockout experiments in mice clearly show independent requirements for INSL3/RXFP2 and androgens in testicular descent; nevertheless causative mutations in INSL3, RXFP2, AR (androgen receptor) or the Leydig cell regulator NR5A1 (steroidogenic factor-1), are rare in cases of cryptorchidism." (PMID 30083133, 2018). "Moreover, there are several clues that support the INSL3 decrease in cryptorchidism as a causal factor, rather than a consequence." (PMID 30687232, 2018). "Thus it appears that cryptorchidism and hypospadias might have common roots in a disruption of Leydig cell function and the production of INSL3 and androgens during early-mid gestation." (PMID 29740335, 2018). "Thus INSL3, possibly as a result of exposure to EDs, such as phthalates, would increase earlier and decline sooner, and thus be out of synchrony with other ongoing morphological processes, thereby encouraging cryptorchidism and/or hypospadias." (PMID 29740335, 2018). "This study examines how evolutionary relaxation and functional change of INSL3 and RXFP2 relate to natural cryptorchidism in mammals." (PMID 41219539, 2025). "Genetic alterations of INSL3 and its receptor RXFP2 were correlated not only with cryptorchidism but also with azoospermia and crypto-/azoospermia." (PMID 41595460, 2025). "In French case-control studies on cryptorchidism, cord blood levels of BPA correlated negatively with cord blood INSL3 levels and unconjugated BPA levels correlated positively with cord blood T and inhibin B levels." (PMID 34690925, 2021). "Although the causality between reduced INSL3 and cryptorchidism could not be demonstrated and BPA levels during fetal life were not measured, the study stressed that the INSL3 pathway should be investigated when studying the in vivo effects of these environmental endocrine disruptors." (PMID 32046352, 2020). "The statistic parameters of UCH-L1, INSL3, AMH and inhibin B concentrations in plasma of children diagnosed with hernia and cryptorchidism." (PMID 29401475, 2018). "The Nr2f2 cKO testes were not able to produce sufficient testosterone and INSL3 to facilitate proper genital differentiation and testicular descent, resulting in hypospadias and cryptorchidism." (PMID 40295478, 2025). "A French case–control study has demonstrated the negative correlation between blood BPA levels and INSL3 levels leading to cryptorchidism." (PMID 37886048, 2023). "It is to be noted though that INSL3 in second trimester amniotic fluid does not appear to differ significantly between normal male infants and those born with cryptorchidism or hypospadias." (PMID 35464060, 2022). "INSL3 and RXFP4, two genes encoding a ligand–receptor pair implicated in cryptorchidism (absence of testes from the scrotum due to their failure to descend), are lost in several Afrotheria that have naturally lost testicular descent." (PMID 33575564, 2020). "However, in the second trimester, amniotic fluid INSL3 does not differ significantly between normal male infants and those born with cryptorchidism or hypospadias." (PMID 37189986, 2023). "The mentioned authors supposed that spontaneous descent, with no treatment or surgical treatment, does not change the final result of INSL3 values or AMH levels in a unilateral acquired undescended testis because treatment does not influence the opposite testis." (PMID 37189986, 2023). "Mutation analysis of INSL3/RXFP2 genes has been suggested in patients with a history of cryptorchidism, and mutations in the NR5A1 gene are emerging as a significant cause of primary spermatogenic impairment associated or not with cryptorchidism." (PMID 32486230, 2020).
cryptorchidism (continued). "Transgenic overexpression of relaxin did not prevent cryptorchidism in Insl3-knockout animals." (PMID 17623071, 2007). "Lastly, although no BPA increase was first detected in newborn boys with undescended testes in France, recent data from this group showed a negative correlation between the cord blood concentrations of BPA and Insulin like 3 (INSL3)." (PMID 25999913, 2015).
hypospadias (12 papers, 2014 to 2025). Hypospadias is the displacement of the urethral meatus on the ventrum of the penis. "This panel shows that in the early second trimester, when amniotic fluid INSL3 is maximal, both cryptorchid and hypospadias cases have significantly elevated INSL3 concentration compared to controls." (PMID 29740335, 2018). "Comparing the cryptorchid and hypospadias cases with controls, particularly within the physiologically informative weeks 13–16, indicates firstly, a small mean increase of INSL3 concentration in both cryptorchid and hypospadias cases." (PMID 29740335, 2018).
hypogonadism (10 papers, 2011 to 2025). A disorder characterized by decreased function of the gonads. "Low levels of circulating INSL3 are evident during hypogonadism, male infertility, and normal aging, but little is known about possible phenotypes associated with this low INSL3 concentrations." (PMID 30323788, 2018). "INSL3 could be therefore responsible for, or contribute to, some clinical signs of hypogonadism currently attributed to testosterone deficiency." (PMID 22216350, 2011). "In middle-aged and older men, individual INSL3 values correlate with and predict morbidity, in part because they reflect the capacity of the testes to produce androgens, with low INSL3 (<0.4 ng/ml) being a good index for clinical hypogonadism." (PMID 40496564, 2025). "We have also shown that in middle-aged and older men with so-called “compensated” hypogonadism, where elevated gonadotropins have promoted testosterone production to normal eugonadal levels, circulating INSL3 still remains significantly reduced." (PMID 38473059, 2024). "An individual who has low INSL3 at age 40 years is therefore likely to have low INSL3 and potentially functional hypogonadism in older age, suggesting that INSL3 has important predictive value as a clinical parameter." (PMID 35770372, 2022). "INSL3 is an emerging biomarker for hypogonadism, with the greater day to day consistency of INSL3 than testosterone being advantageous in this context." (PMID 26192622, 2015). "Reduced plasma concentrations of INSL3 are seen in situations of undifferentiated or altered Leydig cell status (such as hypogonadism and ageing), and INSL3 has been suggested to be even more sensitive than testosterone to impaired Leydig cell function." (PMID 22216350, 2011). "Importantly, in younger men reduced INSL3 appears to predict hypogonadism and hence later health and morbidity." (PMID 40605237, 2025). "Moreover, all patients undergoing testosterone treatment had serum INSL3 values below -3 SD scores, which is in line with previous studies of testosterone-treated males with hypogonadism." (PMID 34447353, 2021). "Indeed, it is worth noting that hypogonadism can just partly justify bone fragility in KS, and additional factors should be taken into account, such as decreased vitamin D and insulin-like factor 3 (INSL3) concentrations, sarcopenia and genetic factors." (PMID 35992104, 2022). "Thus, a reduction in INSL3 synthesis by the Leydig cells might itself lead to a reduced capacity to make T, thereby exacerbating the hypogonadism." (PMID 36425465, 2022). "Circulating INSL3 was assessed in the EMAS cohort and its cross-sectional and longitudinal relationships to hypogonadism, here defined by testosterone (T) <10.5nmol/l, and a range of age-related morbidities determined by correlation and regression analysis." (PMID 36425465, 2022). "Importantly, even though T output may be acutely compensated by increasing LH in cases of compensated hypogonadism, INSL3 measurement implies a decreased Leydig cell capacity to produce T, which is not yet reflected by decreased T itself or other indications of hypogonadism." (PMID 36425465, 2022). "However, in cases of milder testicular abnormalities known as subclinical hypogonadism, there are no apparent variation of T levels but low serum levels of INSL3 are present." (PMID 30323788, 2018).
Infertility (8 papers, 2021 to 2025). "The generation of mutant mice for Insl3 resulted in viable organisms, but presented a clinical bilateral cryptorchid phenotype due to gubernaculum deficiencies, leading, thus, to defective spermatogenesis and later infertility." (PMID 37189986, 2023). "RNA-seq analysis was performed on testes from WT, INSL3-KI, and INSL3-KO mice at three key developmental stages (P8, P23, and P40) to investigate the molecular basis of infertility in cryptorchid KI mice." (PMID 41219539, 2025). "A key factor likely contributing to infertility in cryptorchid INSL3-KI mice is the abnormally elevated inflammatory response in the testes during the first wave of postnatal spermatogenesis." (PMID 41219539, 2025). "MED25 was previously shown to play a critical role in the endoplasmic reticulum stress response Here, a number of the DEPs identified in the current work, including TSPAN8, SUMO3, INSL3, and MED25, were implicated in obesity-related infertility or subfertility." (PMID 34016141, 2021). "Knockout studies in mice have confirmed that the absence of Insl3 or its receptor in females results in partial infertility, marked by a decrease in follicle numbers, ovulations, and litter size." (PMID 39765742, 2024).
thyroid cancer (6 papers, 2015 to 2022). "RXFP2 is also a receptor for INSL3 (insulin-like peptide 3) and has been implicated with tumor-promoting activity in thyroid cancer." (PMID 25857299, 2015). "A growing number of studies have studied the potential of INSL3 in clinical diagnosis or prognosis in various diseases, such as atrophy and weakness in skeletal muscle, klinefelter syndrome, and thyroid cancer." (PMID 34233048, 2021). "INSL3 was also demonstrated to promote early tumor cell invasiveness in human thyroid carcinoma cells by enhancing their metabolic activity and elastin-degrading potential via increasing the production of the lysosomal enzymes cathepsin-L and cathepsin-D." (PMID 34211824, 2021). "INSL3 could promote tumor growth and angiogenesis in nude mice model of thyroid cancer in a manner that appeared to be related to the action of RXFP2 and the secretion of S100A4 and (pro-) cathepsin-L." (PMID 35178089, 2022). "Besides, INSL3 increased the motility of thyroid carcinoma cells and high plasma INSL3 level was found in metastatic ovarian cancer, indicating that INSL3 was involved in the cancer development." (PMID 31032367, 2019).
Klinefelter syndrome (5 papers, 2021 to 2025). A sex chromosome disorder caused by the presence of an extra X chromosome in the male karyotype. "Using this assay, INSL3 concentrations were lower in both untreated boys with Klinefelter syndrome (n=83) or hypogonadotrophic hypogonadism (n=103)." (PMID 36523592, 2022). "The clinical discrepancy between low serum INSL3 and relatively higher testosterone has also been observed by our group in untreated patients with Klinefelter syndrome." (PMID 34447353, 2021). "Testicular expression of INSL3 has been described in several studies, including as an indicator of mature Leydig cells, declining with increasing age, and in dysgenetic testes from patients with Klinefelter syndrome." (PMID 34447353, 2021).
male infertility (5 papers, 2015 to 2025). The inability of the male to effect fertilization of an ovum after a specified period of unprotected intercourse. "Several human genes are known with mutations causing male infertility (AR; AZF gene families; CFTR, DM-1, DNAH gene family, FGFR1, FSHR, INSL3, KAL-1, LGR8-GREAT, LHR, POLG)." (PMID 26097523, 2015). "Studies show that INSL3 levels are even more sensitive for Leydig cell impairment than androgen levels, especially in cases of male infertility in which testosterone levels may be preserved while INSL3 levels are reduced." (PMID 31052376, 2019). "Both genes are necessary for gubernacular function, as knockout of RXFP2 or INSL3 in mice results in the absence of the gubernaculum and no testicular descent, which in turn leads to spermatogenesis defects and male infertility." (PMID 29953435, 2018).
Obesity (5 papers, 2019 to 2025). Accumulation of substantial excess body fat. "This study aims to investigate the association between polycystic ovary syndrome (PCOS) and obesity and insulin resistance (IR) with respect to anti-Müllerian hormone (AMH), inhibin A (INH-A), inhibin B (INH-B), and insulin-like peptide 3 (INSL3) levels, all factors which may have an impact on IR." (PMID 31286756, 2019). "When comparing INSL3 levels in adolescent males with and without obesity, significantly lower levels were found in boys with obesity, suggesting significantly reduced Leydig cell function in these boys." (PMID 31052376, 2019). "In this study, we aimed to investigate the relationship of obesity/IR with hyperandrogenemia and the levels of specific biomarkers (AMH, INSL3, INH-B, and INH-A) that may have an impact on IR and contribute to emergence of disease in adolescent girls with PCOS." (PMID 31286756, 2019). "Moreover, one study in adolescent males with obesity showed a negative correlation between INSL3 and leptin levels (r = −0.468, p = 0.001), further illustrating leptin’s association with reduced Leydig function and hypogonadism." (PMID 31052376, 2019). "However, INSL3 was not investigated in adolescent girls with PCOS in terms of IR and/or obesity." (PMID 31286756, 2019).
osteoporosis (5 papers, 2011 to 2022). A condition of reduced bone mass, with decreased cortical thickness and a decrease in the number and size of the trabeculae of cancellous bone (but normal chemical composition), resulting in increased fracture incidence. "In fact, young adult men with inactivating mutations of the INSL3 receptor have reduced bone mass and higher risk of osteopenia and osteoporosis despite normal testosterone and INSL3 plasma concentrations." (PMID 22216350, 2011). "Testicular dysfunction determines reduced T levels, along with low INSL3 and 25-hydroxyvitamin D levels, and consequently may lead to an increased risk of osteopenia and osteoporosis." (PMID 24688542, 2014). "Besides a possible role for INSL3 in osteoporosis in men, this decline in Leydig cell function adds to the growing debate about whether or not to supplement older men with testosterone." (PMID 33859571, 2021). "Firstly, and strongly supported by the present findings, INSL3 is known to promote bone metabolism, with genetic defects in the receptor RXFP2 in mice and humans both leading to osteoporosis and osteopenia, and with clear effects on bone cells in culture." (PMID 36425465, 2022).